RBMXP1 (RBMX pseudogene 1)
Synonyms: HNRNP-G; formerly HNRPG
Gene: Processed pseudogene on chromosome 6 (48,213,604 to 48,214,794, reverse strand). Ensembl gene ENSG00000216835.
Diseases named in the same sentence as RBMXP1 in open-access papers:
RBMXP1 is named in the same sentence as 1 disease in open-access papers, as found by Europe PMC text mining. Sharing a sentence is not in itself a finding about the gene and the disease.
RBMXP1 shares sentences with these, for which no sentence is quoted: Obesity (1 paper).